UHRF1 (ubiquitin like with PHD and ring finger domains 1)
Diseases named in the same sentence as UHRF1 in open-access papers (continued):
Sharing a sentence is not in itself a finding about the gene and the disease.
cervical cancer (17 papers, 2013 to 2024). A primary or metastatic malignant neoplasm involving the cervix. "Besides cervical cancer, the diagnostic and prognostic capabilities of UHRF1 as biomarker have also been evaluated in ovarian cancer, which is the major worldwide contributor in gynecological tumors posing serious threat to the life of women." (PMID 28881702, 2017). "Plumbagin down-regulates the expression of UHRF1 at both the transcript and protein levels, which leads to the inhibition of metastasis and inhibition of the proliferation of cervical cancer cells." (PMID 37630248, 2023). "UHRF1 regulates UBE2L6 gene expression by promoting its hypermethylation in cervical cancer cells to induce apoptosis." (PMID 33568199, 2021). "Another study on cervical squamous cell carcinoma (CSCC) also reported high expression of UHRF1 at both mRNA and protein level in 47 samples and found that silencing of UHRF1 in cervical cancer cells inhibited cell proliferation and induced apoptosis." (PMID 28881702, 2017). "UHRF1 expression in cervical cancer is also a good indicator for cellular proliferation and malignancy." (PMID 28881702, 2017). "Among cancer tissues that highly express UHRF1 (compared with normal tissues), we found lymph node, colon, and cervical cancers by immunohistochemical staining." (PMID 25765655, 2015). "To test whether UHRF1 participate in DSBs, we treated human cervical cancer HeLa cells with increasing doses of irradiation (IR)." (PMID 39341501, 2024). "Upregulated UHRF1 silences GSN to suppress the death of early cervical cancer cells in CESC." (PMID 37035750, 2023). "Indeed, polyphenolic extracts from plant sources were found to downregulate UHRF1 in the cervical cancer HeLa cell line." (PMID 28881702, 2017). "Interestingly, among the tissues in which we observed UHRF1 upregulation, lymph node, colon and cervical cancers exhibited G9a downregulation." (PMID 25765655, 2015). "Altogether our results show that G extract mediates its growth inhibitory effects on human cervical cancer HeLa cell line likely via the activation of a p16INK4A -dependent cell cycle checkpoint signalling pathway orchestrated by UHRF1 and DNMT1 down-regulation." (PMID 23688286, 2013). "The aim of this study was to determine, in HeLa cervical cancer cell line, whether Limoniastrum guyonianum aqueous gall extract and luteolin, one of the most common flavonoids, could target UHRF1 and DNMT1 expression with subsequent cell cycle arrest and apoptosis via up-regulation of p16INK4A gene." (PMID 23688286, 2013). "UHRF1 acts as an oncogene in various cancers, including melanoma, and downregulates UBE2L6 in cervical cancer." (PMID 36906655, 2023). "The reasons why UHRF1 is overexpressed in cervical cancer, is still not yet elucidated and again it is rather the downstream events that have been deciphered in cellular models." (PMID 28881702, 2017). "UHRF1 had not previously been linked to FOXM1 or OAC but has been shown to be overexpressed in a wide range of other cancers and consistent with our observations of high levels in late stage OAC, has also been shown to be a marker for tumour aggressiveness in cervical cancer." (PMID 25889361, 2015).
leukemia (17 papers, 2015 to 2025). A malignant (clonal) hematologic disorder, involving hematopoietic stem cells and characterized by the presence of primitive or atypical myeloid or lymphoid cells in the bone marrow and the blood. "On one hand, mutations in PHD finger proteins like PHF6 exacerbate leukemia progression, while on the other hand, proteins such as UHRF1 regulate essential pathways in ESCC, affecting tumor growth and therapy resistance." (PMID 38813086, 2024). "Our results show that UHRF1 is indispensable for self-renewal of LICs and loss of Uhrf1 delays leukemia development and initiation." (PMID 36302855, 2022). "Spearman correlation analyses between UHRF1 mRNA levels and the gene expression of MYC family members (MYC, MYCN, and MYCL1), as well as CDK4 and CDK6 in the Haferlach and Gu leukemia datasets, indicated positive associations between UHRF1 and c-Myc, CDK4, and CDK6 in ALL." (PMID 36077796, 2022). "The suppression of UHRF1 downregulates leukemia stem cell signatures and MYC-related pathways in AML cells." (PMID 40508126, 2025). "Both deletion of UHRF1 or overexpression of its downstream target secreted frizzled-related protein 5 (SFRP5) resulted in the inhibition of leukemia cell proliferation, promoting cellular apoptosis and induction of cell cycle arrest." (PMID 40301374, 2025). "This overexpression of UHRF1 is essential for the aberrant self-renewal of leukemia-initiating cells, which drives AML cell proliferation." (PMID 40429796, 2025). "Western blot results showed higher protein expression levels of UHRF1 in Reh and Nalm6 cells compared to other leukemia cell lines (BALL-1, Jurkat, Molt4, MV4-11, and Kasumi), as well as in the normal B lymphoblastoid cell line HMy2.CIR." (PMID 40301374, 2025). "Previously, we found that UHRF1 is upregulated in leukemia and that UHRF1 acts in the AML cell line HL-60 and other cancers via G9a-mediated transcriptional regulation." (PMID 37573395, 2023). "To investigate the role of Uhrf1 in leukemia maintenance, we utilized Uhrf1 conditional knockout mice for AML studies." (PMID 36302855, 2022). "In this study, we showed that deletion of UHRF1 significantly prolongs the survival time of the mice with AML by targeting the self-renewal of leukemia initiating cells through SAP30-mediated MXD4 activation." (PMID 36302855, 2022). "Uhrf1 deficiency significantly decreased the number of CFU and CAFC colonies derived from the mouse MLL-AF9-expressing c-Kit+ leukemia blast cells." (PMID 36302855, 2022). "An analysis of human leukemia transcriptomic datasets revealed concordant overexpression of UHRF1 in B-Cell and T-Cell ALL compared with CLL, AML, and CML." (PMID 36077796, 2022). "An initial analysis of UHRF1 protein expression was performed using leukemia cells from subjects with Philadelphia-positive (Ph+) or Philadelphia-like (Ph-like) ALL (n = 56 subjects) and with AML (n = 76 subjects)." (PMID 36077796, 2022). "A comparison of UHRF1 mRNA expression among B-ALL subtypes in the Gu leukemia dataset revealed the UHRF1 gene expression to be highest in the ETV6-RUNX1 subtype (Figure A1 in the Appendix A)." (PMID 36077796, 2022). "The Western blotting analysis showed that Uhrf1 was significantly depleted in the leukemia cells of Uhrf1fl/flMx1-Cre recipients upon the poly(I:C) administration." (PMID 36302855, 2022). "Specifically, it was shown that the increased expression of G9a along with the transcription factor YY1 specifically repressed UHRF1 transcription during TPA-mediated leukemia cell differentiation." (PMID 36077796, 2022). "In our study, we investigated the expression of UHRF1 in leukemias, which revealed the enrichment of UHRF1 in T-cell and B-cell ALL compared with CLL, AML, and CML." (PMID 36077796, 2022). "To examine the recruitment of G9a before and after leukemia cell differentiation, we performed ChIP assays and real-time PCR on the UHRF1 promoter before and after TPA treatment." (PMID 25765655, 2015).
leukemia (continued). "Using ChIP analysis, we found that UHRF1 was among the transcriptionally silenced genes during leukemia cell differentiation." (PMID 25765655, 2015). "The boxplots of UHRF1 methylation status were decreased in leukemia patient samples compared to those in normal samples." (PMID 25765655, 2015). "The decrease in Pol II and histone acetylation occupancies indicate that UHRF1 is transcriptionally repressed during leukemia cell differentiation." (PMID 25765655, 2015). "To confirm the methylation status of UHRF1 CpG sites in leukemia patient samples through DNA methylation array, we produced a bisulfite sequencing primer for the same region of the DNA methylation array." (PMID 25765655, 2015). "Having identified G9a as an epigenetic transcriptional regulator of UHRF1, we next examined the DNA methylation status of UHRF1 in different leukemia patient samples." (PMID 25765655, 2015). "We suggest that transcription of the oncogenic aspects of UHRF1 is activated by various leukemia-inducing conditions." (PMID 25765655, 2015). "In this paper, we further describe the extended role of H3K9 HMTase G9a in leukemia cells by showing its negative regulation of UHRF1 transcription." (PMID 25765655, 2015). "Using a DNA methylation profiling array, we discovered that the UHRF1 promoter was hypomethylated in samples from leukemia patients, further supporting its overexpression and oncogenic activity." (PMID 25765655, 2015). "In summary, this study demonstrates that negative regulation of UHRF1 transcription by G9a is important in regulating the oncogenic activity of UHRF1 and leukemia cell differentiation." (PMID 25765655, 2015). "Together, these results suggest that transcription of UHRF1 is downregulated by G9a during leukemia cell differentiation." (PMID 25765655, 2015). "We found that increased expression of G9a along with transcription factor YY1 specifically represses UHRF1 transcription during TPA-mediated leukemia cell differentiation." (PMID 25765655, 2015). "To obtain further evidence of UHRF1 involvement in leukemogenesis, we searched the Oncomine database to compare the expression levels of UHRF1 in different types of leukemia with those in normal tissues." (PMID 25765655, 2015). "The importance of the transcriptional regulation of UHRF1 during leukemia cell differentiation was further suggested by our ChIP and real-time PCR analysis." (PMID 25765655, 2015). "Similarly in leukemia, UHRF1-mediated DNA methylation has been shown to regulate self-renewal vs. differentiation cell fates of individual hematopoietic stem cells (HSC) via epigenetic regulation of HSC division." (PMID 29899856, 2018). "We found UHRF1 to be upregulated in leukemia compared to normal tissues." (PMID 25765655, 2015). "Interestingly, UHRF1 was hypomethylated in ALL-type leukemia patient samples compared with AML-type leukemia patient samples." (PMID 25765655, 2015). "ChIP and real-time PCR analysis found that RNA polymerase II (Pol II) and histone acetylation in the UHRF1 promoter were significantly reduced during 12-O-tetradecanoylphorbol-13-acetate (TPA)-mediated leukemia cell differentiation, indicating that the oncogene UHRF1 was tightly repressed." (PMID 25765655, 2015). "This indicates transcriptional repression of UHRF1 upon leukemia cell differentiation." (PMID 25765655, 2015). "Consequently, our data are consistent with previous results that showed hypomethylation of the UHRF1 promoter that resulted in higher expression in leukemia patient samples." (PMID 25765655, 2015). "During leukemia cell differentiation, G9a expression increased and UHRF1 expression decreased." (PMID 25765655, 2015). "Notably, among the genes distinguished between the two groups, the methylation status of the UHRF1 promoter was downregulated in leukemia patient samples." (PMID 25765655, 2015).
leukemia (continued). "Moreover, hypomethylation of the UHRF1 promoter in leukemia patients further suggests its higher expression in undifferentiated cellular conditions." (PMID 25765655, 2015). "Therefore, we hypothesized that upregulated UHRF1 expression might be correlated with G9a expression in different types of cancers, including leukemia." (PMID 25765655, 2015). "Several genes from this group, such as UHRF1, MPZL1, CDK14, RACGAP1, RAB13, and others have oncogenic functions in various solid tumors, leukemias, and lymphomas either predicting poor prognosis, involved in tumor migration, metastasis, or maintenance." (PMID 38464090, 2024). "To further identify the role of Uhrf1 in AML progression, we transplanted 1 × 105 MLL-AF9-expressing Uhrf1fl/fl or Uhrf1Δ/Δ leukemia cells into sublethally irradiated recipient mice." (PMID 36302855, 2022). "Suppressing UHRF1 triggered a unique gene signature in AML cells, including downregulation of the leukemia stem cell and MYC pathways." (PMID 36302855, 2022). "In our study, we investigated the expression levels of UHRF1 in ALL and found that UHRF1 was statistically significantly elevated in ALL compared with its level in other types of leukemia, both at the protein and gene expression levels." (PMID 36077796, 2022). "Thus, UHRF1 may play a role in maintaining leukemic stem cells (LSCs) self-renewal via regulation of DNA methylation and may be considered as a potential target for leukemia treatment." (PMID 29899856, 2018). "On the other hand, TPA treatment induces leukemia cell differentiation by recruiting YY1 and G9a and represses transcription of UHRF1 via H3K9, a methylation-mediated silencing mechanism." (PMID 25765655, 2015). "To investigate whether the level of UHRF1 expression changes during leukemia cell differentiation, we treated HL-60 with TPA and monitored UHRF1 expression patterns using real-time PCR and western analysis." (PMID 25765655, 2015). "We found that UF146 significantly delayed the leukemia development in the Uhrf1fl/fl group but not in the Uhrf1Δ/Δ group, indicating that UF146 specifically targets Uhrf1 in vivo." (PMID 36302855, 2022). "Interestingly, wild type UHRF1 overexpression, but not SRA UHRF1 mutants, was able to decrease p16INK4A expression indicating that UHRF1 negatively controls the expression of p16INK4A in leukemia cells." (PMID 27839516, 2016).
pancreatic cancer (16 papers, 2016 to 2025). "Results from both in vitro as well as in vivo studies have shown that UHRF1 supports pancreatic cancer metastasis and plays a causative role in the development of pancreatic carcinoma." (PMID 29899856, 2018). "High levels of UHRF1 have also been reported in several studies on pancreatic cancer, supporting the use of UHRF1 as a diagnostic marker for pancreatic cancer." (PMID 28881702, 2017). "All these results suggest UHRF1 as a valuable independent diagnostic marker for pancreatic cancer in clinical settings." (PMID 28881702, 2017). "In summary, the majority of pancreatic tumours over‐express nuclear UHRF1 and its over‐expression is associated with larger tumours." (PMID 26497117, 2016). "Moreover, UHRF1 expression in pancreatic cancer was inversely associated with patient survival." (PMID 29899856, 2018). "Together, our findings demonstrate that the pharmacological inhibition of the G9a/DNMT1/UHRF1 complex enhances the cytotoxic response to conventional chemotherapeutic agents in pancreatic cancer cells." (PMID 39810240, 2025). "UHRF1 can facilitate the occurrence and development of various digestive tract tumors, including gastric, colon, and pancreatic cancers, etc.." (PMID 37768204, 2023). "Meanwhile, UHRF1 is considered to be an important regulator of pancreatic cancer cell proliferation, metabolism, and metastasis." (PMID 35656341, 2022). "Cui and coworkers reported elevated levels of UHRF1 expression in pancreatic cancer tissue samples, relative to adjacent healthy tissue samples." (PMID 29899856, 2018). "It is clear that the ability of UHRF1 to regulate Nrf2 levels contributes to the growth potential of pancreatic cancer cells." (PMID 26497117, 2016). "The expression of UHRF1 in pancreatic cancer cells stimulates growth and protects from stress through increasing Nrf2 activity." (PMID 26497117, 2016). "Depletion of Keap1 alone led to a substantial increase in the growth of pancreatic cancer cells, whereas depletion of UHRF1 alone led to a reduction." (PMID 26497117, 2016). "In our experiments, depletion of K‐Ras reduced UHRF1 levels, consistent with a recent report of enhanced UHRF1 expression in response to oncogenic Ras in pancreatic cancer cells." (PMID 26497117, 2016). "UHRF1 depletion from all pancreatic cancer cell lines examined was accompanied by diminished cell numbers, as evidenced by phase‐contrast microscopy, immunocytochemistry and MTS assay." (PMID 26497117, 2016). "Mechanistically, depletion of UHRF1 reduced global and tumour suppressor promoter methylation in pancreatic cancer cell lines, and KEAP1 gene promoter methylation was reduced in one of three cell lines examined." (PMID 26497117, 2016). "Taken together, these data indicate that UHRF1 promotes the growth of pancreatic cancer cells by reducing Keap1 levels and inducing activation of Nrf2." (PMID 26497117, 2016). "Our data suggest that the Keap1–Nrf2 pathway is activated in pancreatic cancer cell lines through UHRF1‐mediated suppression of Keap1 protein levels, with Keap1 promoter methylation potentially contributing to this." (PMID 26497117, 2016). "Of note, K‐Ras, a potent oncogenic driver of pancreatic cancer, which lies upstream of Nrf2 6, was unaffected by UHRF1 depletion from Suit‐2 cells, which harbour oncogenic K‐Ras." (PMID 26497117, 2016). "UHRF1 expression was observed in 20% (5 of 25) of benign pancreatic ducts compared to 86% (114 of 132) of pancreatic tumours, and an inverse relationship between UHRF1 and Keap1 levels in PDAC tumours (n = 124) was apparent (p = 0.002)." (PMID 26497117, 2016). "Similarly, UHRF1 overexpression was observed in 86% (114 of 132) of malignant pancreatic tumors samples and 158 pancreatic cancer samples." (PMID 28881702, 2017).
pancreatic cancer (continued). "Thus, loss of UHRF1 is accompanied by an increase in cellular oxidative stress, suggesting that UHRF1, through the suppression of Keap1 expression, activates Nrf2, which protects pancreatic cancer cells from oxidative stress." (PMID 26497117, 2016). "Western blotting revealed variable levels of UHRF1 in pancreatic cancer cells." (PMID 26497117, 2016). "To test this, we depleted K‐Ras from pancreatic cancer cells and probed for UHRF1 and Keap1." (PMID 26497117, 2016). "UHRF1 is a multi‐domain protein important for cell growth 17 and is over‐expressed in breast 18, 19, bladder 20, 21, colorectal 22, 23, lung 24, 25 prostate 26 and pancreatic cancers." (PMID 26497117, 2016). "Moreover, UHRF1 promotes cell proliferation through the suppression of SIRT4 in pancreatic cancer." (PMID 35847357, 2022). "However, few investigations are carried out to know whether UHRF1 induced the migration and metastasis of pancreatic cancer cells." (PMID 30352833, 2018). "For example, Costello and colleagues reported that UHRF1 maintains KEAP1 promoter methylation, thus regulating the Nrf2 pathway in pancreatic cancer." (PMID 36166308, 2022). "UHRF1, an USP7 substrate, has been observed in many cancer tissues such as breast, bladder, kidney, lung, prostate, cervical and pancreatic cancers." (PMID 27780924, 2016). "UHRF1 drives aerobic glycolysis and proliferation via inhibiting SIRT4 in pancreatic cancer." (PMID 39709438, 2024). "However, UHRF1 levels alone were not sufficient to explain all Keap1 expression patterns in human pancreatic cancers, with occasional high UHRF1 expressers nonetheless expressing detectable Keap1, while some patients lacking UHRF1 also lacked Keap1." (PMID 26497117, 2016).